SNHG16 (small nucleolar RNA host gene 16)
Diseases named in the same sentence as SNHG16 in open-access papers (continued):
Sharing a sentence is not in itself a finding about the gene and the disease.
gastric cancer (8 papers, 2016 to 2024). A primary or metastatic malignant neoplasm involving the stomach. "Although previous studies have reported that SNHG16 was a gastric cancer cell-favorite molecule, our results for the first time demonstrated the roles of SNHG16 in 5-Fu-resistant gastric cancer." (PMID 36447254, 2022). "Here, we report that SNHG16 as well as PTBP1, which is an RNA-binding protein, are positively associated with 5-Fu resistance to gastric cancer." (PMID 36447254, 2022). "For instance, increased SNHG16 expression in human gastric cancer can promote in vitro proliferation and in vivo growth of gastric tumors." (PMID 34722629, 2021).
lung carcinoma (7 papers, 2018 to 2024). "For instance, increased expression of SNHG16 has been shown to be associated with poor prognosis of lung cancer." (PMID 35646120, 2022). "Collectively, the results of current study are supportive of the growth regulatory role of SNHG16 in lung cancer." (PMID 35646120, 2022). "Collectively, the study unveils the molecular role of SNHG16 in regulating the development of lung cancer by interacting with ALDH2." (PMID 35646120, 2022). "Further, SNHG16 expression was found to be enhancing with the progression of each pathological stage of lung cancer." (PMID 35646120, 2022). "Collectively, these findings indicated a possible regulatory role of SNHG16 in lung cancer." (PMID 35646120, 2022). "The study highlights the prognostic and therapeutic role of SNHG16 in lung cancer and advocates the targeting of SNHG16/ALDH2 axis as potential and novel anticancer strategy against the devastating malignancy of human lung cancer." (PMID 35646120, 2022).
colon cancer (6 papers, 2020 to 2023). "Through lasso regression analysis, we selected seven optimal RNA construction models, namely, AGAP3, NHSL1, ENOPH1, NRG1, SNHG16, hsa-mir-1271-5p, and hsa-mir-26b-5p, to predict the prognosis of patients with colon cancer." (PMID 34692670, 2021). "Snhg16 has been proven to affect the viability of colon cancer cells." (PMID 34692670, 2021). "However, in colon cancer, it was reported that SNHG16 downregulation is related to shorter overall survival (OS) of patients." (PMID 32944244, 2020). "Small nucleolar RNA host gene 16 (SNHG16) overexpression leads to the downregulation of miR-302a-3p expression via promoting AKT expression to induce the proliferation of colon cancer cells, thus participating in the growth of colon cancer." (PMID 38002356, 2023). "A total of 709 autophagy-related genes were identified in colon cancer tissues, and 11 autophagy-related lncRNAs (AL138756.1, LINC01063, CD27-AS1, LINC00957, EIF3J-DT, LINC02474, SNHG16, AC105219.1, AC068580.3, LINC02381, and LINC01011) were finally selected and set as prognosis-related lncRNAs." (PMID 36035142, 2022).
liver cancer (6 papers, 2019 to 2026). An epithelial or non-epithelial malignant neoplasm that arises from the liver. "Analysis of clinical samples revealed that the expression levels of SNHG1, SNHG3‐7, SNHG16, SNHG20, and MEG8 (Maternally expressed 8, also known as SNHG23) are associated with clinical indicators of liver cancer patients." (PMID 41474641, 2026). "Notably, the expression of SNHG16 is significantly elevated in liver cancer tissues and cell lines, where it exerts oncogenic effects through pathways such as miR-17-5p/p62, miR-4500/STAT3, and miR-605-3p/TRAF6/NF-κB." (PMID 40427707, 2025). "However, after that, at least 5 studies have reported that SNHG16 is upregulated in liver cancer tissue specimens and cells." (PMID 32944244, 2020). "Additionally, some in vivo experiments indicated that SNHG1, SNHG5, SNHG6, SNHG8, DANCR, SNHG16, and SNHG17 can promote lung metastasis of human liver cancer cells in immunodeficient mice." (PMID 41474641, 2026).
pancreatic cancer (4 papers, 2020 to 2021). "In pancreatic cancer, SNHG16 upregulation is associated with TNM stage, tumor differentiation, and distant metastasis." (PMID 32944244, 2020). "Using Oil Red O staining analysis, Yu and colleagues found that knockdown of lncRNA Small nucleolar RNA host gene 16 (SNHG16) can block lipogenesis and inhibit the progression of pancreatic cancer." (PMID 32973402, 2020). "LncRNA Small Nucleolar RNA Host Gene 16 (SNHG16), an SNHG member, is up-regulated and functions as an oncogene in pancreatic cancer and gastric cancer." (PMID 32025219, 2020).
Sepsis (4 papers, 2020 to 2021). Sepsis is defined as life-threatening organ dysfunction caused by a dysregulated host response to infection. "We explore the role of small nucleolar RNA host gene 16 (SNHG16) in sepsis-mediated acute lung injury (ALI) and inflammation." (PMID 34092219, 2021). "We studied the downstream target of SNHG16 to investigate the specific mechanism of SNHG16 in sepsis-induced ALI." (PMID 34092219, 2021). "Downregulation of SNHG16 reduced the apoptosis and inflammation in sepsis-induced ALI." (PMID 34956235, 2021). "Therefore, we speculate that there’s a regulatory axis of SNHG16/miR-128-3p/HMGB3 in sepsis-mediated ALI." (PMID 34092219, 2021). "H19, SNHG16, and NEAT1 are also involved in sepsis progress." (PMID 33204219, 2020).
acute lymphoblastic leukemia (3 papers, 2019 to 2021). Leukemia with an acute onset, characterized by the presence of lymphoblasts in the bone marrow and the peripheral blood. "In acute lymphoblastic leukemia (ALL) and acute myeloid leukemia (AML) patients and cell lines, the lncRNA small nucleolar RNA host gene 16 (SNHG16) overexpresses, and by lowering CELF2 mRNA stability, this lncRNA enhances proliferation and migration." (PMID 34681716, 2021).
atherosclerosis (3 papers, 2019 to 2025). A disease characterized by the build-up of fatty material and calcium deposition in the arterial wall resulting in partial or complete occlusion of the arterial lumen. "Thirdly, PDGF‐bb was used to induce the up‐regulation of SNHG16; however, other pathogenic stimuli may also involve the development of atherosclerosis." (PMID 31441592, 2019). "Conversely, the inhibition of SNHG16 leads to opposing results, suggesting SNHG16 as a potential target for atherosclerosis treatment." (PMID 38170281, 2024). "A PCSK9 inhibitor was found to mitigate atherosclerosis by modulating the small nucleolar RNA host gene 16 (SNHG16)/enhancer of zeste homolog 2 (EZH2)/TNF receptor-associated factor 5 (TRAF5) axis, thereby restraining the migration, proliferation and formation of foam cells by VSMCs." (PMID 40354375, 2025). "Thus, in vivo studies will be our future directions to look at the therapeutic effects of targeting SNHG16 in an animal of atherosclerosis." (PMID 31441592, 2019). "Whether targeting SNHG16 could provide effective therapy for atherosclerosis may require further investigation." (PMID 31441592, 2019). "Importantly, the investigation of clinical plasma samples from patients with atherosclerosis showed the up‐regulation of SNHG16 and Smad2, and down‐regulation of miR‐205." (PMID 31441592, 2019). "The present study investigated the role of long non‐coding RNA (lncRNA) small nucleolar RNA host gene 16 (SNHG16) in the human aortic smooth muscle cell (HASMC) proliferation and migration and explored the potential link between SNHG16 and atherosclerosis." (PMID 31441592, 2019).
diabetic nephropathy (3 papers, 2021 to 2023). "Studies in recent years have found that SNHG16 induces proliferation and fibrosis of chylomicron cells in mice with diabetic nephropathy." (PMID 37280692, 2023). "It has been revealed that SNHG16 is overexpressed in the serum of diabetic nephropathy patients, high glucose-treated podocytes, and mesangial cells." (PMID 35207562, 2022). "Therefore, the investigation of the mechanism by which SNHG16 affects diabetic inflammation and diabetic nephropathy through competitive binding of miR-212-3p is also an innovative point of our study." (PMID 37280692, 2023). "Therefore, SNHG16 seems to contribute to diabetic nephropathy via KLF9-induced oxidative stress by directly interfering with miR-106a." (PMID 35207562, 2022). "Besides, SNHG16 could induce proliferation and fibrogenesis via modulating miR-141-3p and CCND1 in diabetic nephropathy." (PMID 34290731, 2021).
ovarian carcinoma (3 papers, 2019 to 2025). A malignant neoplasm originating from the surface ovarian epithelium. "MEG3, SNHG16, MNX1-AS1, and ZFAS1 are confirmed to be associated with ovarian cancer in the Lnc2cancer database, and their PMIDs are 28175963, 29461589, 29271994, and 28154416, respectively." (PMID 33980147, 2021). "Recent study showed that SNHG1 and SNHG16 can regulate the activity of matrix metalloproteinases (MMPs) to promote EMT, and then influence the invasion and migration abilities of ovarian cancer cells." (PMID 41200835, 2025).
COVID-19 (2 papers, 2021 to 2023). A disease caused by infection with severe acute respiratory syndrome coronavirus 2. "We reported lower expressions of SNHG6 and SNHG16 in COVID-19 patients of both sexes compared with sex-matched controls." (PMID 34147082, 2021). "Down-regulation of SNHG16 in COVID-19 patients might result in decreased proportion of γδ1 T cells, thus activation of pro-inflammatory cascades and pulmonary fibrosis, since some subsets of γδ T cells regulate immunosuppressive functions and induce immune tolerance in certain contexts." (PMID 34147082, 2021). "Among them, small nucleolar RNA host gene 16 (SNHG16) can activate the TGF pathway and participate in inflammatory cascades; its expression was found to be downregulated in COVID-19 cases compared to controls." (PMID 38057315, 2023).
diabetes (2 papers, 2021 to 2023). "A recent study has demonstrated that upregulation of SNHG16 promotes diabetes-associated retinal vascular endothelial cell (RMEC) dysfunction by activating the NF-κB and PI3K/AKT pathways, but the exact mechanism remains unclear." (PMID 37280692, 2023). "Previous studies have found that SNHG16 upregulation can activate NF-kB and PI3K/AKT pathways to promote diabetes-associated RMEC dysfunction." (PMID 37280692, 2023). "SNHG16 has been less studied in the field of diabetes mellitus, and the pathological basis of cancer is also an inflammatory response." (PMID 37280692, 2023). "Further experiments were performed to assess the function of SNHG16 in diabetic kidney injury in diabetes." (PMID 37280692, 2023). "In the present study, we investigated the role of SNHG16 in regulating NF-κB via miR-212-3p in diabetes inflammation, providing new insights for the development of future diabetes therapies." (PMID 37280692, 2023). "Elucidating the mechanism of SNHG16 in diabetic inflammation could provide new directions for the treatment of diabetes." (PMID 37280692, 2023). "To explore the participation of SNHG16 in diabetes-induced retinal endothelial cell dysfunction, we examined the expression level of different isoforms of SNHG16 in hRMECs cultured under HG or LG condition for 48 h, imitating diabetic and normal circumstances, respectively." (PMID 33898104, 2021). "To further explore the mechanism by which SNHG16 could regulate diabetes-related hRMEC dysfunction, we performed a series of transcription factor transactivation assays." (PMID 33898104, 2021).
endometrial carcinoma (2 papers, 2020 to 2023). A malignant tumor arising from the epithelium that lines the cavity of the uterine body. "In endometrial carcinoma, TFAP2A transcriptionally induces small nucleolar RNA host gene 16 (SNHG16) expression by binding to the promotor, leading to tumor growth and glycolysis." (PMID 37291585, 2023).
pulmonary fibrosis (2 papers, 2021). Chronic progressive interstitial lung disorder characterized by the replacement of the lung tissue by connective tissue, leading to progressive dyspnea, respiratory failure, or right heart failure. "To investigate the role of SNHG16 in pulmonary fibrosis, we used shRNA which specifically targets SNHG16 to knockdown the expression of SNHG16." (PMID 33549106, 2021). "The aim of this study was to clarify the regulatory role of SNHG16 and mechanisms of its down-stream factors in pulmonary fibrosis." (PMID 33549106, 2021). "The expression of SNHG16 was significantly up-regulated in bleomycin-(BLM) induced lung fibrosis and transforming growth factor-β (TGF-β)-induced fibroblast." (PMID 33549106, 2021). "However, whether SNHG16 plays regulatory roles in lung fibrosis remains unknown and still needs to be explored." (PMID 33549106, 2021).
retinoblastoma (2 papers, 2019 to 2021). A malignant tumor that originates in the nuclear layer of the retina. "In other types of cancers, including retinoblastoma, oral squamous cell carcinoma, nasopharyngeal carcinoma, SNHG16 sequesters a number of miRNAs, namely miR-140-5p, miR-182-5p, miR-128-3p, miR-183-5p, miR-17-5p, and miR-520a-3p." (PMID 34671603, 2021). "In xenograft models of retinoblastoma, up-regulation SNHG16 or its downstream target NRAS can increase tumor growth." (PMID 34671603, 2021).
asthma (1 paper, 2022). "The top five AUCs for DElncRNAs of the T2 asthma and healthy control groups included PCAT19 (AUC = 0.949), TP53TG1 (AUC = 0.876), SNHG16 (AUC = 0.852), LINC01133 (AUC = 0.844), and PP7080 (AUC = 0.827)." (PMID 35480331, 2022). "Similarly, the following results showed that the DElncRNAs with the top five AUCs of the T2 asthma and non-T2 asthma groups: PCAT19 (AUC = 0.914), COLCA1 (AUC = 0.827), SLC9A3-AS1 (AUC = 0.824), SNHG16 (AUC = 0.802), and LINC01133 (AUC = 0.793)." (PMID 35480331, 2022).
autoimmune disease (1 paper, 2023). A disorder resulting from loss of function or tissue destruction of an organ or multiple organs, arising from humoral or cellular immune responses of the individual to their own tissue constituents. "Expression of SNHG16, TLR4 and TRAF6 and cell death processes were examined in lung tissues and peripheral blood (PB) leukocytes from AH patients associated with SLE and other autoimmune diseases, and in the lungs and spleen from a pristane-induced C57BL/6 mouse AH model." (PMID 37700342, 2023).
B-cell lymphoma (1 paper, 2022). "SNHG16 has been widely described as an oncogenic factor in a variety of cancers, including B-cell lymphoma." (PMID 35740344, 2022).
colorectal tumor (1 paper, 2019). "Besides the ones that were reported to be dysregulated in colorectal tumor samples, such as CCAT1, H19, DANCR, ZFAS1, SNHG16, CYTOR, we have identified many others in this study including LUCRC." (PMID 32082365, 2019).
intracerebral hemorrhage (1 paper, 2022). A cerebrovascular disorder characterized by bleeding into one or both cerebral hemispheres including the basal ganglia and the cerebral cortex. "SNHG16 is related to MAPK1, which is one of the key genes in ferroptosis; SNHG16 is also involved in intracerebral hemorrhage." (PMID 36011284, 2022).
laryngeal squamous cell carcinoma (1 paper, 2025). A squamous cell carcinoma that arises from the larynx. "In laryngeal squamous cell carcinoma (LSCC), the lncRNA small nucleolar RNA host gene 16 (SNHG16), a putative oncogene, shows elevated expression in both cells and tissue." (PMID 40421201, 2025).
lung diseases (1 paper, 2021). "Besides, SNHG16 is abnormally expressed in other lung diseases, including ALI." (PMID 34092219, 2021).
melanoma (1 paper, 2022). A malignant, usually aggressive tumor composed of atypical, neoplastic melanocytes. "For instance, SNHG16, TTN-AS1, and MALAT1 are overexpressed in melanoma and exert oncogenic effects." (PMID 33674778, 2022).
multiple myeloma (1 paper, 2024). "For instance, the lncRNA small nucleolar RNA host gene 16 (SNHG16) plays an oncogenic role by promoting cell cycle progression and suppressing apoptosis in multiple myeloma cells." (PMID 38886753, 2024).
osteoarthritis (1 paper, 2024). A noninflammatory degenerative joint disease occurring chiefly in older persons, characterized by degeneration of the articular cartilage, hypertrophy of bone at the margins and changes in the synovial membrane. "It was reported that CCND1 and SNHG16 were upregulated in the cartilage tissues of osteoarthritis, and SNHG16 could promote the progress of osteoarthritis by regulating miR‐93‐5p/CCND1 axis." (PMID 39555740, 2024).
systemic lupus erythematosus (1 paper, 2024). An autoimmune multi-organ disease typically associated with vasculopathy and autoantibody production. "The conserved lncRNA SNHG16 (Small Nucleolar RNA Host Gene 16) participates in the systemic lupus erythematosus-associated alveolar hemorrhage (SLE-AH) pathogenesis via regulating autophagy and neutrophil extracellular traps (NETs) formation." (PMID 39036601, 2024).